RNU6-833P (RNA, U6 small nuclear 833, pseudogene)
Gene: Small nuclear RNA gene on chromosome 10 (73,279,062 to 73,279,168, forward strand). Ensembl gene ENSG00000200356.
Homologues: Orthologues: chimpanzee U6 (100% identical), macaque U6 (93% identical), guinea pig U6 (85% identical), dog U6 (79% identical). Paralogues in human: RNU6-616P (87% identical), RNU6-15P (86% identical), RNU6-468P (86% identical), RNU6-21P (85% identical), RNU6-33P (85% identical), RNU6-463P (85% identical), RNU6-574P (85% identical), RNU6-61P (85% identical), RNU6-1 (84% identical), RNU6-1011P (84% identical), RNU6-1060P (84% identical), RNU6-1103P (84% identical), and 1284 more.